BECN1 (beclin 1)
Diseases named in the same sentence as BECN1 in open-access papers (continued):
Sharing a sentence is not in itself a finding about the gene and the disease.
tumor (continued). "Indeed, caspase-1 cleaved the haploinsufficient tumor suppressor Beclin-1 that was also upregulated by H11/HspB8 through a TAK1/mTORC1 pathway that involved mTOR phosphorylation at S2481, which is the site of intrinsic mTORC1-specific catalytic activity." (PMID 23056924, 2012). "We did not investigate the levels of these heterodimers in our tissues, but it is clear that liver tissues with chronic liver damage (caused by either HBV or HCV infection) expressed higher levels of Beclin 1, Bcl-xL and Bad transcripts than peritumoral or tumor tissues." (PMID 22928777, 2012). "The restoration of Beclin 1 expression inhibits tumor cell proliferation and tumor growth." (PMID 22200845, 2012). "Beclin 1 is a tumor suppressor gene product that allosterically activates the class III phosphatidylinositol 3-kinase (PI3KC3), which is essential for the recruitment of other autophagy-related gene (Atg) proteins to the phagophore assembly site (PAS) to initiate autophagosome formation." (PMID 23270461, 2012). "Besides, while heterozygous disruption of BECN1 gene promotes tumor development, the overexpression inhibits tumorigenesis, supporting the idea that defective autophagy or autophagy inhibition plays a role in malignant transformation." (PMID 22295229, 2011). "Previous studies indicted that the constant activation of MEK/ERK signaling in tumor cells could up-regulate Beclin-1, eventually activating autophagy." (PMID 22164300, 2011). "The most important evidence linking dysfunctional autophagy and cancer comes from studies demonstrating that autophagy inhibition in mice, by disruption of BECN1, increases cellular proliferation as well as mammary hyperplasia and accelerates tumor development." (PMID 22295229, 2011). "In addition to tumor formation, we also directly examined the effect of Beclin 1 gene dosage on ROS levels." (PMID 21611191, 2011). "Finally, to determine if Beclin 1 would be rate limiting in a model with intermediate latency and penetrance, a tumor watch was performed on Lck-Bax1 mice that were either Beclin 1 wild type or heterozygous." (PMID 21611191, 2011). "In addition, since mitophagy was activated in Lck-Casp9DN mice, we also examined oncogenesis in tumor-prone mice with impaired autophagy (Beclin 1+/−)." (PMID 21611191, 2011). "To examine the oncogenic potential of this transgenic line, we determined the rate of tumor formation in Lck-Casp9DN mice crossed to Lck-Bax38/1 and Beclin 1+/− mice, two tumor-prone strains in which altered mitochondrial function has been implicated in oncogenesis." (PMID 21611191, 2011). "Although a direct involvement of an activated autophagic machinery in cancer cell survival and growth cannot be excluded, Beclin 1 overexpression may be an indirect marker of tumour aggressiveness." (PMID 20842118, 2010). "Importantly, beclin-1's NES is also required for the protein's function in autophagy as well as its tumor suppressor activity." (PMID 20352102, 2010). "Silencing the Beclin 1 protein may prove lethal for tumours whose survival relies on intensified autophagic cell response, such as tumours with high hypoxic cell content." (PMID 20842118, 2010). "Thus, the reduced expression of Beclin-1 could decrease the autophagic removal of damaged organelles, facilitating cell death and tumor clearance." (PMID 40002858, 2025). "In addition, we observed that HMGB1 and BECN1 expression increased with tumor stage." (PMID 41164196, 2025). "Importantly, the tumor-suppressive effect of DHX9 knockdown was reversed by BECN1 downregulation." (PMID 40659605, 2025). "A large number of studies have found that autophagy inhibitors target LC3, p62, beclin-1 and autophagy associated gene 5 (Atg5) in conjunction with PTT, while inhibiting the AKT/mTOR signaling pathway, significantly enhancing the autophagy activity in tumor cells." (PMID 40688079, 2025).
tumor (continued). "For instance, in cells with defective apoptosis mechanisms, autophagy often serves as an alternative cell death pathway; however, in cells where key autophagy genes are mutated or deleted, such as BECN1 or ATG5, autophagy may fail to execute its tumor-suppressive role effectively." (PMID 39315094, 2024). "Consistently, the activation of the Akt/mTOR pathway decreased with ALO treatment in NSCLC cells in vitro and mouse tumor models in vivo, whereas the levels of Beclin‐1 and ATG7 increased, indicating that ALO may promote autophagosome formation by interfering with the Akt/mTOR pathway." (PMID 39166458, 2024). "However, lack of association of BECN1 expression and tumor size, PR and HER2 positivity was observed in agreement with our studied cohort." (PMID 38787424, 2024). "In our study, we investigated the expression of BECN1 in a BC female Egyptian patient cohort, as well as its prognostic role through evaluating its association with disease free survival (DFS) after 2 years follow up and association of tumor clinicopathological features." (PMID 38787424, 2024). "While a conclusive connection between tumor suppression and autophagy in human cancer has not been established, subsequent research has indicated the occurrence of allelic loss or reduced expression of BECN1 in various other forms of cancer." (PMID 39436197, 2024). "For the experimental endpoint, tumor tissue was harvested, and Western blot analysis showed that the levels of Beclin-1 phosphorylation at Ser-295, and mTOR at Ser-2448 were significantly reduced in the combination group, while Beclin-1 phosphorylation at Thr119 was significantly promoted." (PMID 39795061, 2024). "Events hinting at such a protective role have been described: Beclin-1 overexpression in breast cancer cell line MCF-7 decreases tumor formation in nude mice, while the mutation in the domain of Beclin-1 interacting with the Vps34 complex reverses these tumor suppression functions." (PMID 36765741, 2023). "Beclin 1-derived peptide, which is able to initiate autophagy pathway also acting as a tumor suppressor, was modified with a cysteine residue and could thus be grafted onto PDA NPs through the sulfur group by mixing in an aqueous solution under an argon atmosphere." (PMID 37298641, 2023). "Thus, BECN1 only exerts a tumor suppressor effect in genetic animal models of cancer." (PMID 36197606, 2022). "Moreover, we found that cell transfection with an hsa-miR-30a-3p mimic blocks protective autophagy through ATG5, ATG12, and Beclin 1 suppression, which in turn increases cancer cell sensitivity to chemotherapeutic interventions in vitro and reduces tumor growth and muscle invasion in vivo." (PMID 35449123, 2022). "Tat-BECN1 increases the release of insulin in murine and human primary islets (Tat-BECN1 is also reported to reduce adenosine-stimulated insulin secretion in islets), the secretion of candidate protein biomarkers of tumor cell autophagy, and the production of monoclonal antibody in CHO cells." (PMID 36172279, 2022). "The last strategy develops soluble Beclin 1 peptide-containing fusion proteins, where thioredoxin (Trx) confers solubility and thermal stability, pH low insertion peptide (pHLIP) triggers the fusion protein translocation across the plasma membrane in a tumor acidic environment." (PMID 36172279, 2022). "In addition, miR-30a has been shown to sensitize tumor cells to cisplatin by lowering beclin-1-mediated autophagy, suggesting that boosting miR-30a levels in tumor cells could be a novel way to improve chemotherapy’s efficacy during cancer treatment." (PMID 35326612, 2022). "There are various proteins like Bcl-2-interacting Beclin1 (BECN1/ATG6), Atg4c, Bax-interacting factor-1 (Bif-1), BH3-only proteins, DAP kinase, ultraviolet radiation resistance-associated gene (UVRAG), and PTEN involved in autophagy that shows its role in tumor suppression." (PMID 33628386, 2021).
tumor (continued). "In the 1990s, by analyzing human breast carcinoma cell lines, deletions of the key autophagy protein BECN1 were identified in 9 out of the 22 cell lines analyzed; this research led to consider and investigate in depth the autophagy process as a putative key step in tumor suppression." (PMID 34830777, 2021). "In addition, autophagy-related gene are reported as tumor suppressor including BECN1 and Atg5." (PMID 33802602, 2021). "The average level of mRNA expression of BECN1 and BRCA1 in the 240 tumors with shallow deletion CNV was lower than the corresponding level in the 50 tumors with diploid CNV, indicating that the monoallelic loss of the tumor suppressor gene reflected in lower mRNA expression." (PMID 33670664, 2021). "For instance, tumorigenesis might occur following abnormal expression of proteins controlling autophagy such as BECN1, considered a tumor suppressor monoallelically found in several types of tumors while downregulated in others, such as hepatocellular carcinoma." (PMID 34685652, 2021). "Additionally, Beclin-1 polymer inhibits tumour growth and retards in vivo tumour development." (PMID 34575883, 2021). "Moreover, beclin-1 acts as both autophagy mediator and tumor suppressor." (PMID 33233671, 2020). "However, whether the tumour-suppressive activities of Beclin 1 require its autophagic or endocytic functions remain to be further explored." (PMID 32873152, 2020). "In addition, beclin 1 expression was lower in HCC tissues than in non-cancerous tissues and positively correlated with the 5-year survival rate of HCC patients, suggesting that beclin 1-mediated autophagy during HCC progression acts as a tumor-suppressing mechanism." (PMID 32235537, 2020). "Moreover, it has been described that cisplatin or 5-fluorouracil promotes cytoprotective autophagy through upregulation of Beclin-1 in bladder cancer cells, an effect that has also been reported in other tumor cells, such as laryngeal, ovarian, esophageal, and colon cancer models." (PMID 33194736, 2020). "Furthermore, RIPK3 depletion reversed the effect of Beclin 1 depletion on tumour growth, which was induced by treatment with birinapant and emricasan, suggesting that depletion of Beclin 1 might be accelerating the necroptotic processes in the tumour model." (PMID 32457484, 2020). "In addition, upstream positive regulators of Beclin-1, such as UV radiation and Bax interacting factor-1 (Bif-1), have been found downregulated in several types of human cancers and an increased tumor incidence has been reported in Beclin1 heterozygous mice." (PMID 33330070, 2020). "al. demonstrated that active EGFR binds to beclin-1, inhibiting its autophagy function in non-small cell lung cancer (NSCLC), and EGFR-mutated NSCLC cells presented improved tumor progression and partial tumor resistance to therapy with tyrosine kinase inhibitors." (PMID 33233671, 2020). "Furthermore, treatment of HER2+ breast cancer xenografts with the autophagy-inducing peptide Tat-Beclin 1 inhibits tumor growth as efficiently as the tyrosine kinase inhibitor Lapatinib does, disrupts the Beclin 1-HER2 complex, and induces a unique transcriptional profile." (PMID 31877888, 2019). "These may contribute to the tumor suppressor function of Beclin-1." (PMID 30107804, 2018). "A peptide designed to specifically block the interaction between the MHV68-encoded homolog of Bcl-2 M11 and BECN1 (therefore, preventing M11-mediated downregulation of autophagy) could be used to both restore the tumor suppressor activity of BECN1 and to limit the reservoir of viral latency." (PMID 29207540, 2017). "In addition, breast cancer 1 (BRCA1) is a tumor suppressor located close to Beclin-1 on the genome." (PMID 28753959, 2017). "Lentiviral-Fhit infection clearly resulted in a two-fold reduction in tumor volume compared with lentiviral-LacZ, and this antitumor effect was markedly increased in xenografts of autophagy-suppressed H460 cells which stably express shRNA against beclin-1 or LC3B." (PMID 28404875, 2017).
tumor (continued). "We next evaluated whether CaMKII binds to Beclin 1 in tumor cells." (PMID 29079782, 2017). "However, the inhibition of autophagy by Beclin-1 knockdown showed an increase in apoptosis and decrease in cell viability, thus autophagy could also have cytoprotective roles in stressed tumour cells." (PMID 28320471, 2017). "Previous report also shows O2-• bust to damage cancer cells under high fluence LPLI, which suggest that H2O2 may trigger RelA/BECN1-mediated autophagy as a survival mechanism, whereas O2-• confers to tumor suppressive effects in cancer cells under LPLI exposure." (PMID 27632526, 2016). "In addition to BECN1, frameshift mutations in core autophagy genes ATG2B, ATG5, ATG9B and ATG12 in colorectal cancers have been reported, providing additional evidence for a tumour suppressive role." (PMID 27256984, 2016). "Furthermore, metastatic tumor samples, primary ascites cell cultures, and early-passage cell lines generated at our institute exhibited a similar trend in Beclin-1 protein expression." (PMID 26239434, 2015). "Overexpression of Beclin-1 in mice could develop excessive autophagy to prevent tumor development." (PMID 25821829, 2015). "Previous studies have shown that mutation of the nuclear export signal of Beclin 1 (resulting in its nuclear retention) or deletion of the evolutionary conserved domain of Beclin 1 (which abrogates it binding to VPS34 and autophagy function) blocks its tumor suppressor activity." (PMID 25693418, 2015). "Therefore, beclin-1 expression may have a dual role in breast carcinogenesis, acting both to promote and to suppress tumor progression." (PMID 25955408, 2015). "The impacts of Beclin 1 on tumor progression may be at least partly independent from autophagy." (PMID 26506105, 2015). "Therefore, Beclin-1 – and autophagy by extension – are thought to be tumor suppressive." (PMID 26239434, 2015). "It was found that chemical carcinogen-induced hepatocarcinoma could be suppressed by enhanced autophagy which removed aggresome and damaged organelles that could lead to DNA double strand break and genome instability, while mice with Beclin-1 knockout are tumor prone." (PMID 25821829, 2015). "Moreover, many studies indicate that decreased Beclin 1 function contributes to tumour growth." (PMID 26008601, 2015). "Therefore, Beclin-1 could play a role as a tumor suppressor and its decreased expression may contribute to the development of human cancer." (PMID 24885292, 2014). "Therefore, we hypothesize that Beclin 1 may play an important role in limiting tumor formation in a Lck-Casp9DN transgenic model." (PMID 21611191, 2011). "It was also found that extensive overexpression of Beclin 1 was correlated with markers of both the presence of hypoxia and cellular adaptation to hypoxia, providing further evidence supporting the favourable role of hypoxia-induced autophagy in tumor cell survival." (PMID 22190938, 2011). "Interestingly, tumor formation in Beclin 1+/− does not involve complete loss of the Beclin 1 protein or gene." (PMID 21611191, 2011). "Our study sought to delineate the molecular underpinnings of BCc1's anti-tumor effects in a BALB/c murine model of BC, focusing on key autophagy regulators (Beclin-1, ATG-4B, ATG-7) and the mTOR signaling axis." (PMID 41550506, 2026). "Then, the protein expression levels of the autophagy markers, p62 and Beclin-1, and glycolysis markers, GLUT1 and HK2, in tumor tissue were determined." (PMID 40969279, 2025). "The gastrocnemius muscles in the tumor-only group exhibited significantly in-creased expression of MURF-1, Beclin-1, and LC3-II compared to the control group (p < 0.001)." (PMID 40136406, 2025). "At present, the autophagy pathways in tumor cells are relatively complex, with the AMPK/mTOR/p70S6K signaling pathway and the Beclin-1 signaling pathway being particularly relevant to autophagy in BC." (PMID 40688079, 2025).
tumor (continued). "PE supplementation significantly decreased the expression of MURF-1, Beclin-1, and LC3-II induced by tumor cell injection (p < 0.05)." (PMID 40136406, 2025). "The overexpression of PDK4 and miR-122 effectively reversed the effects of OA and overexpressing PDK4 on the protein expression levels of Beclin-1, p62, GLUT1, and HK2 in the tumor tissue, respectively (P<0.05)." (PMID 40969279, 2025). "After administering OA, the protein expression level of Beclin-1 was prominently up-regulated, and the protein expression levels of p62, GLUT1, and HK2 were markedly down-regulated in the tumor tissue (P<0.0001)." (PMID 40969279, 2025). "Conversely, enhancing basal autophagy through genetic manipulation or the use of Tat-Beclin 1 peptide to disrupt the HER2/Beclin 1 interaction and induce autophagy effectively inhibits HER2-driven tumor growth." (PMID 40723786, 2025). "It reduced PD-L1 and Rab11 content of TEX, altered tumor cell size/shape, induced vesicle accumulations in the cytosol, and upregulated expression levels of autophagy-related proteins, ATG7, Beclin-1, and LC3." (PMID 40121518, 2025). "Promoter hypermethylation and histone deacetylation can silence ATG5, BECN1, and LC3B, thereby suppressing autophagy and promoting tumor survival." (PMID 41329030, 2025). "When we verified BECN1 and BCL2 expression levels in the M0, M1 and M2 macrophage subtypes in DLBCL and non-tumor control samples, we found that they were overexpressed in M0 and M1 but not in M2 macrophages." (PMID 41415285, 2025). "BECN1, ELAVL1, and ATG16L1 were highly expressed in tumor tissues, while NCOA4, FTH1, FTL, SNCA, TNF, ATG7, and ZFP36 showed low expression levels." (PMID 39593730, 2024). "Research has demonstrated that suppression of autophagy-related genes, such as Beclin-1 and ATG5, diminishes the migratory and invasive potential of tumor cells, attributed to reduced availability of energy and materials essential for these processes." (PMID 39655055, 2024). "Glabridin induces tumor cell apoptosis by upregulating caspase-3, caspase-8, caspase-9 cleavage while enhancing autophagy by upregulating LC3-II and beclin-1." (PMID 39723390, 2024). "A low expression of Ki67 and PARP and high expression of Beclin-1 and LC3B were found in tumor tissues of xenografts after combination therapy." (PMID 39795061, 2024). "Apparently, normal adjacent to primary tumor presented the weak NLRC5, Beclin 1 and LC3 staining in cervical epithelium layers." (PMID 38961101, 2024). "PVT1 upregulation promoted autophagy and tumor growth in NSCLC cells, with miR-216b interacting with PVT1 and Beclin-1." (PMID 39650649, 2024). "All cases presented staining for NLRC5, Beclin 1 and LC3 were predominantly detected in the cytoplasm of tumor cells." (PMID 38961101, 2024). "Bupivacaine inhibited tumor cell proliferation and migration through AKT/mTOR signaling pathway to increase the expression of Beclin-1 and the expression ratio of light chain 3B-II (LC3B-II)/LC3B-I in NSCLC cells." (PMID 38482052, 2024). "Beclin-1, the mammalian homologue of yeast ATG6/Vacuolar Protein Sorting 30 (Vps30) and also known as the BECN1 gene, is recognized as a tumor suppressor gene." (PMID 38628670, 2024). "The correlation between Beclin‐1 (BECN1) monoallelic deletion and enhanced tumor development is proved in both tumor cell lines and mice model." (PMID 37249289, 2023). "For example, autophagic proteins, including UVRAG (in initiation), BECN1 (in initiation), ATG5 (in elongation), and ATG2B (in fusion), play tumor suppressor roles." (PMID 37006252, 2023). "It has been shown in tumor cells that ROS promote the transport of HMGB1 from the nucleus to the cytoplasm, while cytoplasmic HMGB1 interacts with Beclin-1, which, in turn, is released from the Beclin-1/Bcl-2 complex and induces autophagy." (PMID 37158301, 2023). "Beclin-1 is regulated by EGFR, whose overexpression decreases Beclin-1 levels and promotes tumour progression." (PMID 37174088, 2023).